OR5AP2 (olfactory receptor family 5 subfamily AP member 2)
Description:
Odorant receptor.
Synonyms: OR9J1
Tractability: Antibody: UniProt places it where antibodies can reach, with high confidence; UniProt predicts a signal peptide or a membrane-spanning region; its Gene Ontology location is reachable by antibodies, with medium confidence.
Gene: Protein-coding gene on chromosome 11 (56,641,489 to 56,642,439, reverse strand). Ensembl gene ENSG00000172464.
Subcellular location: Cell membrane
Pathways (Reactome):
Sensory Perception: Expression and translocation of olfactory receptors
Gene Ontology:
Molecular function: olfactory receptor activity; G protein-coupled receptor activity
Biological process: G protein-coupled receptor signaling pathway; sensory perception of smell; detection of chemical stimulus involved in sensory perception of smell
Cellular component: plasma membrane; membrane
Genetic constraint (gnomAD): Loss-of-function variants: 0 observed, 4.45 expected, observed/expected ratio (o/e) 0, 90% interval 0 to 0.67. That is too few expected variants to judge how well the gene tolerates losing a copy. Missense variants: 395 observed, 379.98 expected, observed/expected ratio (o/e) 1.04, 90% interval 0.96 to 1.13. Synonymous variants: 134 observed, 141.89 expected, observed/expected ratio (o/e) 0.94, 90% interval 0.82 to 1.09.
Homologues: Orthologues: chimpanzee OR5AP2 (98% identical), macaque OR5AP2 (96% identical), dog OR5AP2 (90% identical), pig OR5AP2 (87% identical), mouse Or5ap2 (86% identical), rat Or5ap2 (84% identical), rat Or5ap2b (81% identical). Paralogues in human: OR5B12 (56% identical), OR5B21 (55% identical), OR5W2 (55% identical), OR5I1 (54% identical), OR5AS1 (54% identical), OR8U1 (54% identical), OR8U3 (54% identical), OR9H1 (54% identical), OR5J2 (53% identical), OR9I1 (53% identical), OR5AU1 (53% identical), OR5D18 (53% identical), and 84 more.